MST1 (macrophage stimulating 1)
Diseases named in the same sentence as MST1 in open-access papers (continued):
Sharing a sentence is not in itself a finding about the gene and the disease.
ovarian carcinoma (6 papers, 2020 to 2025). A malignant neoplasm originating from the surface ovarian epithelium. "It operates by shielding the SARAH coiled-coil domains of MST1/2, thereby suppressing the Hippo pathway and promoting cisplatin resistance in ovarian cancer." (PMID 39034401, 2024). "Neratinib has been shown to significantly block MST1 activation in β-cells and islets, implying that Neratinib has demonstrated potential as a clinically viable treatment for targeting ovarian cancer peritoneal metastases in the future." (PMID 39198883, 2024). "Furthermore, we have shown that reinstating nuclear YAP1 by specifically inhibiting MST1/2 in TAMs can induce a shift in polarization from M2- to M1-like MФs polarization, offering a viable therapeutic strategy against epithelial ovarian cancer (EOC) peritoneal metastases." (PMID 39198883, 2024). "In mice, ovarian cancer development is regulated through YAP, TAZ, MST1/2, SAV1, and LATS1/2 MST1/2 kinases." (PMID 39595118, 2024). "In ovarian cancer cells treated with WZ10, Western blotting revealed that the expression levels of Hippo-YAP pathway-related proteins MST1/2, LATS1, p-MOB1 and p-YAP were markedly lower than in control cells." (PMID 36498794, 2022). "We detected the level of MST1 and LATS1, which were also the important factors in the Hippo pathway, in ovarian cancer cells." (PMID 32918541, 2020).
pancreatic ductal adenocarcinoma (6 papers, 2019 to 2025). An infiltrating adenocarcinoma that arises from the epithelial cells of the pancreas. "Restored expression of MST1 in suppresses the proliferation, migration, invasion, and cell spheroid formation of pancreatic ductal adenocarcinoma cells through caspase-1–induced pyroptosis." (PMID 33941231, 2021). "It has been shown that mammalian STE20-like kinase 1 (MST1) is decreased in pancreatic ductal adenocarcinoma." (PMID 33941231, 2021). "Our study sheds light on the intricate interplay among GLI1, MST1, and miR-301a, which connects the Hedgehog (Hh) and HIPPO/YAP signaling pathways in pancreatic ductal adenocarcinoma (PDAC)." (PMID 39846248, 2025). "LINC00941 was found to interact with mammalian STE20-like protein kinase 1 (MST1), promoting dephosphorylation of MST1 mediated by protein phosphatase 2A (PP2A) and activating the Hippo pathway, thereby enhancing glycolysis in Pancreatic ductal adenocarcinoma (PDAC)." (PMID 36124026, 2022). "A study reported that the level of MST1 is decreased in pancreatic ductal adenocarcinoma (PDAC) cells, and the restored expression of mammalian STE20-like kinase 1 (MST1) promotes PDAC cells death and suppres the proliferation, migration and invasion of PDAC cells via pyroptosis mediated by ROS106." (PMID 31501419, 2019).
renal fibrosis (6 papers, 2017 to 2025). A final common manifestation of a wide variety of chronic kidney diseases characterized by glomerulosclerosis and tubulointerstitial fibrosis. "We found that experimental DCM arising from cardiac specific overexpression of Mst1 was associated with renal fibrosis, inflammation and loss of GFR." (PMID 29255249, 2017). "Contrary to MST1/2 deficiency in PDGFRα+ cells or tubule cells, MST1/2 deficiency in macrophage inhibited M2 accumulation and fibrosis in the obstructed kidney of mice, revealing the role of MST1/2 in different cells on renal fibrosis." (PMID 38250155, 2024). "cKO mice were used to verify the role of macrophage-MST1/2 in renal fibrosis." (PMID 38250155, 2024). "Mice with myeloid-specific deletion of MST1/2 exhibit enhanced M1 inflammatory response and spontaneously developed M1-related inflammatory disorders, but they are highly resistant to M2-related renal fibrosis." (PMID 38250155, 2024). "Furthermore, mice with nephric duct-specific deletion of Yap1 exhibited defects in ureter-bladder junction, and renal tubule-specific Mst1/2 deletion induced hyperproliferation of renal tubular epithelial cells and renal fibrosis." (PMID 34545930, 2021). "A variety of cells are involved in renal fibrosis of UUO mice model, such as epithelial cells, mesenchymal cells and macrophages, and MST1/2 is widely expressed in these cells." (PMID 38250155, 2024). "In 2020, researchers developed a double-knockout mouse model for MST1/2, key upstream regulators of the Hippo signaling pathway, and demonstrated that deletion of tubular MST1/2 increases YAP expression, thereby promoting renal fibrosis and functional impairment." (PMID 40478495, 2025). "Therefore, the inhibition of MST1/2 in macrophage reduced macrophage M2-type polarization in vivo and in vitro, and XMU-MP-1 impaired renal fibrosis." (PMID 38250155, 2024). "At least, MST1/2 inhibition could reduce the IL-4+IL-13-induced activation of STAT6 and MEK/ERK in macrophage independent and dependent of YAP, and MST1/2 inhibition impaired M2 polarization and renal fibrosis." (PMID 38250155, 2024). "Recently, research contends that the lack of renal tubules Mst1/Mst2 can lead to CKD through the YAP and non-YAP pathways, and the activation of renal tubules YAP contributes to renal fibrosis." (PMID 33897769, 2021).
rheumatoid arthritis (6 papers, 2014 to 2024). A chronic, systemic autoimmune disorder characterized by inflammation in the synovial membranes and articular surfaces. "Hypermethylation of the MST1/STK4 promoter and reduced MST1 expression has also been noted in patients with autoimmune pancreatitis (with extrapancreatic lesions) and rheumatoid arthritis." (PMID 29597279, 2018). "FOXO1 emerges as a critical downstream element of MST1, contributing to the regulatory mechanisms governing dsDNA-induced migration and invasion of RA FLSs, thereby enhancing our comprehension of the intricate signaling dynamics in the pathogenesis of rheumatoid arthritis." (PMID 38765007, 2024). "In this study, we investigated the role of macrophage stimulating 1 (Mst1) and the AMPK-Sirt1 signaling pathway in the oxidative stress-induced mitochondrial dysfunction and apoptosis seen in rheumatoid arthritis-related fibroblast-like synoviocytes (RA-FLSs)." (PMID 32692720, 2020).
thyroid cancer (6 papers, 2010 to 2022). "An inhibitory interaction between BRAFV600E and the related MST1 kinase was observed previously in thyroid cancer." (PMID 36038253, 2022). "This was also described in thyroid cancer cells, in which overexpression of RASSF2 reduced colony formation, because RASSF2 interacts with the proapoptotic kinases MST1 and MST2 and induces apoptosis in these cells." (PMID 26284587, 2015). "Functionally our data show that RASSF2 interacts with the proapoptotic kinases MST1 and MST2 and induces apoptosis in thyroid cancer cell lines." (PMID 20920251, 2010).
atherosclerosis (5 papers, 2019 to 2025). A disease characterized by the build-up of fatty material and calcium deposition in the arterial wall resulting in partial or complete occlusion of the arterial lumen. "However, the exact mechanism underlying the involvement of MST1 in atherosclerosis remains to be elucidated." (PMID 38049831, 2023).
endometriosis (5 papers, 2020 to 2025). The growth of functional endometrial tissue in anatomic sites outside the uterine body. "As an upstream regulator of MAPK, MST1 expression is deficient in peritoneal macrophages of patients with endometriosis." (PMID 36263059, 2022). "Downregulation of Mst1 expression in endometriosis has been reported to promote endometriotic cell proliferation through activation of mitophagy." (PMID 38645639, 2024). "The inhibition of MST1 in macrophages induced by M2-type macrophages was similar to that of endometriosis-related peritoneal macrophages." (PMID 36263059, 2022). "In this study, we found reduced mRNA expression of MST1 (STK4) in peritoneal macrophages of patients with endometriosis, whereas the expression of miR-887-5p as an upstream regulator of MST1 was increased." (PMID 36263059, 2022). "Furthermore, the PINK1-Parkin mitophagy pathway represents a critical mechanism by which macrophage stimulator 1 (Mst1), a negative regulator of endometriosis, modulates apoptosis and migration in human endometrial stromal cells (ESCs)." (PMID 41341128, 2025). "CD68+ peritoneal macrophages (pMφ) co-express MST1 with low expression in endometriosis." (PMID 36263059, 2022). "Therefore, we detected the expression of MST1 in peritoneal macrophages in patients with endometriosis and found that its protein and mRNA levels were decreased." (PMID 36263059, 2022). "The negative regulation of MST1 by miR-887-5p could be one reason for the abnormal peritoneal macrophages in endometriosis." (PMID 36263059, 2022). "However, the regulatory mechanism of MST1 in endometriosis, especially endometriosis-related macrophages, is unknown." (PMID 36263059, 2022). "We presume that MST1 may also regulate the peritoneal immune macroenvironment in endometriosis." (PMID 36263059, 2022). "Moreover, the abnormal expression of MST1 in endometriosis-related peritoneal macrophages could activate autophagy in ectopic endometrial lesions." (PMID 36263059, 2022). "This study focused on the reprogramming of peritoneal macrophages via inducing MST1 deficiency and increasing p38-MAPK expression, which led to an increase in the anti-inflammatory properties of macrophages and promotion of tissue repair, creating higher levels of autophagy in endometriosis lesions." (PMID 36263059, 2022). "In addition, macrophages with MST1 knockdown co-cultured with HESCs activated autophagy in HESCs, and this phenomenon coincided with the autophagy activation state in the ectopic endometrial cells of endometriosis patients." (PMID 36263059, 2022). "Moreover, in endometriosis, Drp1-related mitochondrial fission is also affected by Mst1." (PMID 31951593, 2020). "Subsequently, we artificially knocked down MST1 expression through transfection of miR-887-5p mimics or siRNA-MST1 to transform M0 macrophages (THP-1+PMA), and then co-cultured them with HESCs to simulate the immune environment of ectopic endometriosis." (PMID 36263059, 2022). "Moreover, we detected lower protein and mRNA levels of MST1 and higher levels of p38-MAPK in peritoneal macrophages from patients with endometriosis (vs. non-endometriosis)." (PMID 36263059, 2022).
lymphoma (5 papers, 2018 to 2024). A malignant (clonal) proliferation of B- lymphocytes or T- lymphocytes which involves the lymph nodes, bone marrow and/or extranodal sites. "Previous studies revealed MST1/2 expressed in most organs as well as the haematopoietic system involved in hepatocellular sarcoma, intestinal adenocarcinoma and lymphoma." (PMID 35088536, 2022). "Equally, MST1 - also known as serine/threonine kinase 4 (STK4) - has been described as critical factor for the maintenance of genomic integrity in lymphoma." (PMID 34615513, 2021). "The preceding results reported that MST1 was markedly present in hematopoietic cells, and that knockdown of MST1 could induce the onset of lymphoma by determining chromosomal instability." (PMID 33924049, 2021).
mesothelioma (5 papers, 2017 to 2024). A usually malignant and aggressive neoplasm of the mesothelium which is often associated with exposure to asbestos. "In 2015 the exome sequencing has revealed some mutations and fusions of MST1/2 or LATS1/2 kinases in cancer, for example LATS1 fusion in mesothelioma." (PMID 38163861, 2024). "When mesothelioma cells were stimulated with MST1, strong effects on downstream signaling pathways were observed using antibody based arrays, suggesting that this pathway is both intact and functional in mesothelioma." (PMID 30863365, 2019). "In silico analysis of the TCGA mesothelioma dataset confirmed that high expression of MST1R and MST1 was associated with longer survival." (PMID 30863365, 2019). "In the TCGA mesothelioma cohort, 35 (42%) of 83 patients had mutations in MST1/2, LAST1/2, or NF (negative upstream regulators of YAP)." (PMID 32277165, 2020). "MST1 was found to be ubiquitously expressed at the protein level in mesothelioma cell lines." (PMID 30863365, 2019). "In contrast, a small molecule inhibitor of the MST1R (RON) tyrosine kinase domain (LCRF-0004) had significant effects on mesothelioma cellular proliferation and health, and cell cycle progression, and additions of exogenous MST1 were unable to abrogate these effects." (PMID 30863365, 2019). "Immunohistochemistry for MST1 was subsequently conducted on the same mesothelioma TMA." (PMID 30863365, 2019). "We have identified a novel pathway, the MST1/MST1R (RON) signaling axis, which is overexpressed, activated, and can be targeted pharmacologically in mesothelioma." (PMID 30863365, 2019).
non-alcoholic fatty liver disease (5 papers, 2023 to 2026). "Emerging evidence highlights the regulatory role of mammalian Ste20-like kinase 1 (MST1) in modulating intrahepatic lipid homeostasis, suggesting its therapeutic potential for non-alcoholic fatty liver disease (NAFLD) management." (PMID 40247356, 2025). "Upregulation of Mst1 is also directly correlated with increased severity of inflammation and hepatic injury in non-alcoholic fatty liver disease." (PMID 36831193, 2023). "Notably, several studies have previously shown the inhibitory effect of Mst1 on mitophagy in various disease models, such as cardiac ischemia‒reperfusion models and nonalcoholic fatty liver disease (NAFLD) models." (PMID 38443598, 2024).
Stroke (5 papers, 2021 to 2026). Sudden impairment of blood flow to a part of the brain due to occlusion or rupture of an artery to the brain. "Multiple variants in the SLCO1B1, PRIM1, APOB, TYK2, TSEN15, CYP4F2, and MST1 genes were previously suggested as risk factors for stroke with p-values < 1.0 × 10−5 in a GWAS on German pediatrics." (PMID 37895268, 2023). "Among these, genetically predicted levels of four proteins—ACOX1, FGF5, FURIN, and MST1—also demonstrated evidence of potential causal associations with CAD and/or stroke, supported by observational analysis." (PMID 41065563, 2026). "Proteome-wide MR identified 242 proteins associated with BP, of which 48 were also linked to CAD or stroke, with four (ACOX1, FGF5, FURIN, MST1) also supported by genetic colocalization analyses (FDR 5% and PP ≥70%)." (PMID 41065563, 2026). "Genetically predicted FURIN and FGF5 were strongly associated with BP and stroke risk, while ACOX1, FGF5, and MST1 exhibited potential causal effects on CAD." (PMID 41065563, 2026).
type 2 diabetes (5 papers, 2019 to 2024). "The involvement of the Hippo pathway in the regulation of the apoptotic process resulting from the metabolic changes associated with type 2 diabetes has been documented on the basis of the contribution of its individual elements, including MST1, Merlin (Nf2), LATS2, and YAP." (PMID 35054822, 2022). "This partially explains why symptoms of type 2 diabetes can be alleviated in some cancer patients taking tyrosine kinase inhibitors (for MST1)." (PMID 35054822, 2022). "In summary, neratinib is a previously unrecognized inhibitor of MST1 and represents a potential β-cell-protective drug with proof-of-concept in vitro in human islets and in vivo in rodent models of both type 1 and type 2 diabetes." (PMID 31676778, 2019).
alveolar rhabdomyosarcoma (4 papers, 2019 to 2025). A rapidly growing malignant mesenchymal neoplasm. "Furthermore, MST1 is methylated in 80% of rhabdomyosarcoma, and MST2 is methylated in 50% of synovial sarcoma." (PMID 40983796, 2025). "In alveolar rhabdomyosarcoma cells, the PAX3::FOXO1 fusion transcript has been demonstrated to suppress Hippo signalling through Ras associated domain family 4 (RASSF4) which modulates the activity of the MST1 kinase, leading to overexpression of YAP." (PMID 40983796, 2025). "In alveolar rhabdomyosarcoma, the chimeric PAX3-FOXO1 oncoprotein was found to promote tumorigenesis by inhibition of MST1, and dysregulation of YAP18." (PMID 31873172, 2019).
Alzheimer disease (4 papers, 2013 to 2026). A progressive, neurodegenerative disease characterized by loss of function and death of nerve cells in several areas of the brain leading to loss of cognitive function such as memory and language. "Specifically, microglial YAP and MST1 appear to be putative regulators of microglial biology in the context of Alzheimer’s disease pathology." (PMID 34831369, 2021). "Therefore, we propose targeting MST1 as a promising therapeutic strategy to halt neuroinflammation and progression in Alzheimer's disease." (PMID 41689046, 2026). "Indeed, Mst1 mediated FoxO3 activation in response to β-amyloid (Aβ) has been shown to mediate death of selective neuron in Alzheimer's disease (AD)." (PMID 23985272, 2013). "As such, dysregulation of Hippo signaling, particularly of its core kinases MST1/2 and LATS1/2, has begun to attract attention in the Alzheimer’s disease (AD) field." (PMID 41013661, 2025).
cardiac ischemia (4 papers, 2018 to 2024). "We then evaluated the role of Mst1, FoxO1, and C/EBP-β during 4 h of myocardial ischemia." (PMID 39060225, 2024).
Crohn disease (4 papers, 2009 to 2018). A gastrointestinal disorder characterized by chronic inflammation involving all layers of the intestinal wall, noncaseating granulomas affecting the intestinal wall and regional lymph nodes, and transmural fibrosis. "Interactions between MST1 and other Crohn's disease susceptibility genes also contribute to disease risk." (PMID 29441677, 2018). "Sequence kernel association test analysis identified one locus, namely the rs144982232 in MST1 (A>G, P = 1.78 × 10−5, odds ratio = 4.87), which was significantly associated with Crohn's disease after controlling for multiple testing by Bonferroni method." (PMID 29441677, 2018). "In the targeted captured regions, the synonymous SNP (ie rs144982232) in MST1 was most significantly associated with Crohn's disease in the Chinese population." (PMID 29441677, 2018). "Taken together, our data suggested that a novel locus in MST1 is involved in Crohn's disease in the Chinese population." (PMID 29441677, 2018). "The co‐involvement of NOD2, JAK2, MUC19 and MST1 in mucosal defence and inflammation in Crohn's disease therefore deserves further study." (PMID 29441677, 2018). "Gene‐gene interaction analysis revealed significant interactions between MST1 and other susceptibility genes, including NOD2, MUC19 and ATG16L1 in contributing to Crohn's disease risk." (PMID 29441677, 2018). "The large odds ratios indicated a strong risk effect in the MST1, JAK2 and NOD2 gene to Crohn's disease." (PMID 29441677, 2018). "Another noteworthy observation is that VDR was centred by MUC19, MST1, ATG16L1 and NOD2, which synergistically contributed to Crohn's disease risk." (PMID 29441677, 2018). "Nevertheless, it is important to note that our ImmunoChip data set did not cover MST1 rs144982232 and its association with Crohn's disease has to be consolidated with an independent Chinese cohort." (PMID 29441677, 2018). "While the top ranked genes included some P/PIs previously found to be associated with CD and/or UC, such as MMP2, MMP15 and MST1, a series of P/PI genes were identified, which have not been previously related to Crohn's disease or ulcerative colitis." (PMID 21931648, 2011).
endometrial cancer (4 papers, 2016 to 2022). Primary or metastatic malignant neoplasm involving the endometrium (mucous membrane that lines the endometrial cavity). "MST1/2 kinases were expressed in endometrial cancer cells in approximately a quarter of the cohort (26.7%)." (PMID 36552980, 2022). "Endometrial cancer tissue shows elevated expression of the Ras-related protein Rab-8A, as well as MST1 and PKN1, which could therefore serve as EC biomarkers." (PMID 27595026, 2016).